LRRC43 (leucine rich repeat containing 43)
Synonyms: MGC35140
Tractability: No criterion of Open Targets' tractability assessment is met for any kind of drug.
Gene: Protein-coding gene on chromosome 12 (122,167,738 to 122,203,471, forward strand). Ensembl gene ENSG00000158113.
Subcellular location (Human Protein Atlas): Golgi apparatus; Vesicles
Genetic constraint (gnomAD): Loss-of-function variants: 61 observed, 60.54 expected, observed/expected ratio (o/e) 1.01, 90% interval 0.82 to 1.25. The upper end of that interval is the gene's LOEUF score, 1.25, which puts it in group 5 of 6, group 1 being the genes least tolerant of losing a copy. Missense variants: 841 observed, 833.64 expected, observed/expected ratio (o/e) 1.01, 90% interval 0.95 to 1.07. Synonymous variants: 408 observed, 373.52 expected, observed/expected ratio (o/e) 1.09, 90% interval 1.01 to 1.19.
Homologues: Orthologues: chimpanzee LRRC43 (99% identical), macaque LRRC43 (94% identical), rabbit LRRC43 (70% identical), dog LRRC43 (69% identical), rat Lrrc43 (68% identical), mouse Lrrc43 (67% identical), pig LRRC43 (67% identical), guinea pig LRRC43 (64% identical), tropical clawed frog lrrc43 (37% identical), Drosophila melanogaster TbCMF46 (11% identical), Drosophila melanogaster Ppr-Y (9% identical). Paralogues in human: LRRC9 (15% identical), DNAAF1 (13% identical), LRRCC1 (13% identical), CEP97 (13% identical), LRGUK (13% identical), LRRC49 (11% identical), DRC3 (11% identical), DNAAF11 (10% identical), LRRIQ3 (9% identical), PPP1R42 (8% identical), LRRC46 (8% identical), LRRC23 (7% identical), and 1 more.